ALKBH5 (alkB homolog 5, RNA demethylase)
Diseases named in the same sentence as ALKBH5 in open-access papers (continued):
Sharing a sentence is not in itself a finding about the gene and the disease.
tumor (continued). "In addition, the controversial role of ALKBH5 in different cancers might be the existence of genetic and epigenetic heterogeneities among the cancer cell lines and primary tumor specimens utilized by different research groups." (PMID 37858219, 2023). "Additionally, hypoxia significantly enhanced HIF-1α and ALKBH5 expression in tumor cells." (PMID 36632222, 2023). "Moreover, overexpression of ALKBH5 exerts tumor suppressive effects in pancreatic ductal adenocarcinoma (PDAC) by reducing WIF1 mRNA methylation and regulating the Wnt pathway, leading to downregulation of C-MYC, Cyclin D1, MMP-2, and MMP-9 and sensitizing PDAC cells to gemcitabine." (PMID 37007161, 2023). "Thus, selective ALKBH5 inhibitors such as Ena15 and Ena21 are promising strategies against glioma progression as they could decrease tumor growth in different GBM cell lines." (PMID 37821870, 2023). "Subsequently, we surprisingly observed that ALKBH5 expression level positively correlated with more aggressive clinicopathological characteristics (such as histological differentiation, invasion depth, Tumor, Node, Metastasis (TNM) stage and lymphatic metastasis)." (PMID 36864711, 2023). "Therefore, we hypothesized that ALKBH5 promoted tumor malignant progression of GC in a common environment." (PMID 38007439, 2023). "However, another study showed that ALKBH5 could inhibit tumor cell proliferation and metastasis by directly reducing YTHDFs-dependent YAP1 expression in NSCLC and decreasing YAP1 activity through HuR-dependent control of miR-107/LATS2 expression." (PMID 37007161, 2023). "However, in the HCC background, it is unclear whether ALKBH5 regulates the tumor immune microenvironment." (PMID 35982895, 2022). "Comparing the m6A regulator genes’ expression levels in the tumor group and normal group and investigating their relationship, we found that the expression of ALKBH5 was lower in tumor samples than normal ones and a high level of ALKBH5 led to a better prognosis." (PMID 36686788, 2022). "In addition, ALKBH5 could regulate the content of metabolites and cytokines in the tumor microenvironment during GVAX (a granulocyte-macrophage colony-stimulating factor (GM-CSF) gene-transfected tumor cell vaccine)/anti-PD-1 therapy." (PMID 36226062, 2022). "However, the biological function of ALKBH5 is heterogeneous in various tumours." (PMID 35414790, 2022). "Importantly, a small molecule Alkbh5 inhibitor improved the anti-tumor effects of immunotherapy." (PMID 35646923, 2022). "Furthermore, when the expression level of FTO or ALKBH5 is altered or dysfunctional, it may be involved in the occurrence and progression of a variety of tumors as a tumor suppressor gene or oncogene in an m6A-dependent manner." (PMID 35093087, 2022). "Therefore, we determined whether BMSC-Exos could inhibit the progression of TNBC and whether ALKBH5 shRNA-loaded BMSC-Exos had better tumor-suppressive effects." (PMID 36551544, 2022). "ALKBH5 plays an immunomodulatory role in melanoma, colorectal cancer and other tumors, not only regulating Mct4/Slc16a3 molecules related to tumor survival, metastasis and metabolism, but also affecting the number of tumor-infiltrating Treg cells and bone marrow derived inhibitory cells (MDSC)." (PMID 36618420, 2022). "Numerous epigenetic, HIF-targeted and miRNA-directed therapies have been examined in clinical trials, showing potential of targeting these kinds of molecules for cancer treatment, which might exert anti-tumor effects partly through altering ALKBH5-mediated m6A demethylation." (PMID 35063010, 2022). "However, the role of ALKBH5 in tumor angiogenesis is still unclear." (PMID 36376862, 2022). "Subsequent PPI and survival analysis results demonstrated that UBE2C may be a key downstream gene involved in the ALKBH5 promoting function in the TNBC cell stemness and tumor progression where ALKBH5 regulated the m6A modification of UBE2C and consequently upregulated UBE2C expression." (PMID 36551544, 2022).
tumor (continued). "Moreover, ALKBH5 acts as a tumor suppressor in pancreatic ductal adenocarcinoma (PDAC) and sensitizes PDAC cells to gemcitabine by reducing WIF1 mRNA methylation and modulating the Wnt pathway, which leads to the downregulation of C-MYC, Cyclin D1, MMP-2 and MMP-9." (PMID 35063010, 2022). "ALKBH5, one of the demethylases, could affect tumor progression by regulating lncRNA demethylation." (PMID 35003214, 2021). "The diverse roles played by ALKBH5 might be dependent on the tumor context." (PMID 34112124, 2021). "In addition, KD of ALKBH5 in GSCs displayed extended survival with a lower rate of tumor formation." (PMID 34281602, 2021). "Moreover, previous studies demonstrated that ALKBH5 participates in regulating contents of metabolites (such as lactic acid) in the tumour microenvironment, similarly tumour infiltration of myeloid-derived suppressor cells (MDSCs)and T-regulatory cells (Tregs) through Mct4/Slc16a3." (PMID 34794452, 2021). "However, LKB1 loss alone was not sufficient to change m6A level or ALKBH5 expression or their relationship with aggressive tumor phenotypes." (PMID 34016959, 2021). "In addition, the effects of ALKBH5 on carcinogenesis might relate to the stage of tumor and the different downstream molecules as shown by other epitranscriptomics enzyme such as FTO." (PMID 34112124, 2021). "Moreover, the tumor-suppressive effects of ALKBH5 overexpression were further enhanced by siYTHDF2." (PMID 33431791, 2021). "Similarly, the relative weaker correlation of RNA expression between SLC25A28 and ALKBH5 in tumor samples may also arise from other uncharacterized mechanisms in regulating SLC25A28." (PMID 34733841, 2021). "Our results indicated that Cluster 2, with high expression of ALKBH5 and low expression of YTHDF1, had more immune infiltration, immune checkpoint inhibitor expression, and tumor mutation burden than Cluster 1, hence suggesting that Cluster 2 might respond better to immunotherapy." (PMID 34079761, 2021). "In addition, it was found that ALKBH5 could prevent tumor progression by regulating the posttranscriptional activation of PER1." (PMID 35046996, 2021). "Hence, the profiling prompted a tumour suppressor image of ALKBH5." (PMID 32429928, 2020). "Next, we generated an A549 cell line stably co-expressing ALKBH5 with a control vector (ALKBH5control) or miR-107 mimics (ALKBH5miR-107 m), and a control stable cell line, Vectorcontrol, to explore whether miR-107 was involved in the ALKBH5-mediated tumor growth and metastasis." (PMID 32106857, 2020). "However, mechanistic action of FTO or ALKBH5 for tumor formation remains to be identified." (PMID 33511112, 2020). "Interestingly, opposite trends of YAP and ALKBH5 expression were observed in paired fresh NSCLC tumor cancer tissues (Tumor) and matched adjacent normal tissues (Normal) by RT-PCR, western blotting, and qPCR (left panel, n = 10; right panel, n = 30) (n = 10), and immunohistochemistry (IHC) (n = 10)." (PMID 32106857, 2020). "Additionally, ALKBH5 promoted OS cell proliferation in vitro, and facilitated tumor growth in vivo." (PMID 32021563, 2020). "Importantly, the cell proliferation rates of ALKBH5 knockdown cells after HINT2 knockdown were only partially comparable to those of the control cells with normal ALKBH5 expression (lanes 1, 4, 6G-H), suggesting that there are more tumor-related genes regulated by their m6A modifications." (PMID 31722709, 2019). "To validate the in vitro results, we generated separate A549 cell lines stably expressing ALKBH5, YAP, or ZEB1 to explore their functions in tumor growth and metastasis in vivo." (PMID 41216500, 2026). "In syngeneic tumor models, CD34+ humanized mice, and intestine-specific Alkbh5 transgenic mice, ALKBH5 promoted MDSC accumulation while diminishing NK and CD8+ T-cell infiltration, thereby driving tumorigenesis." (PMID 41562066, 2025).
tumor (continued). "qRT-PCR and western blot analysis showed that, upon ALKBH5 silencing in tumor tissues, ALKBH5 and TUG1 were decreased, while SH3BGRL expression was upregulated (P < 0.01), suggesting that ALKBH5 silencing suppresses AML cell drug resistance to ADR in vivo." (PMID 39465506, 2025). "The writer enzyme METTL3 facilitates tumor growth by stabilizing oncogene mRNA, whereas erasers such as FTO and ALKBH5 suppress tumor progression by removing m6A marks." (PMID 40034695, 2025). "Upregulation of ALKBH5 promotes ferroptosis in NSCLC cells by decreasing SLC7A11 expression, thereby inhibiting tumor invasion and metastasis." (PMID 40740874, 2025). "Demethylation of mML by the erasers, ALKBH5 and FTO, can result in both tumorigenesis and tumor suppression in different cancers." (PMID 40243425, 2025). "Then we separated tumor cells into LGR5+ and LGR5- clusters, revealing significantly higher ALKBH5 expression in LGR5+ cells compared to LGR5- cells." (PMID 41390849, 2025). "In non-small cell lung cancer (NSCLC), ALKBH5 has been found to inhibit TGF-β-induced epithelial-mesenchymal transition (EMT) by regulating the TGF-β/SMAD signaling pathway, thereby suppressing tumor invasion and metastasis." (PMID 40341728, 2025). "ALKBH5 regulates the expression of Mct4/Slc16a3 and affects the abundance of myeloid-derived suppressor cells (MDSC) and Treg in the tumor microenvironment(TME)." (PMID 40483535, 2025). "ALKBH5 is downregulated in pancreatic cancer, in which it normally functions to decrease m6A-methylation of lncRNA KCNK15-AS1, leading to decreased tumor motility." (PMID 40243425, 2025). "Meanwhile, ALKBH5 cKO mice demonstrated attenuated AOM/DSS-induced CRC formation compared to WT mice, as evidenced by significant reductions in tumor multiplicity (P = 0.03) and load (P = 0.047)." (PMID 41390849, 2025). "In line with our data, previous studies have shown that ALKBH5-mediated m6A RNA demethylation specifically affects the expression of CDK inhibitors in several cell types such as γδT cell progenitors and tumor cells." (PMID 40341728, 2025). "Mechanistically, ALKBH5 promotes activation of the JAK2/p-STAT3 pathway in an m6A-dependent manner, facilitating tumor progression." (PMID 41562066, 2025). "The expression of FTO and ALKBH5 has shown discrepancies in studies on RCC patients, with some indicating oncogenic roles and others suggesting tumor-suppressive roles." (PMID 40361322, 2025). "ALKBH5 was found aberrantly overexpressed in AML, and exerted tumor-promoting effects through post-transcriptional regulation of crucial targets such as the prognosis-associated oncogene TACC3, to promote tumorigenesis and self-renewal of cancer stem cell." (PMID 40483535, 2025). "Mechanistically, ALKBH5 stabilized CPT1A expression by demethylation, promoting fatty acid oxidation and energy metabolism to sustain M2 polarization and tumor growth." (PMID 41562066, 2025). "In conclusion, the combined treatment of ALKBH5 siRNA and IGTB1 overexpression vector loaded in NGR-modified BNVs significantly inhibited tumor growth in mice." (PMID 40585991, 2025). "In head and neck squamous cell carcinoma, ALKBH5 inhibits RIG-1 expression and interferon-α production via the IKKε/TBK1/IRF3 pathway, thereby promoting tumor progression." (PMID 40585991, 2025). "Either ALKBH5 knockout or MANF ablation had a more noticeable effect on VHL inactivation 786-O, suggested tumor cell ER stress protective effects and mechanisms of MANF was affected by VHL status." (PMID 40603319, 2025). "UMAP-based expression overlays revealed that NSUN2, YTHDC1, ALKBH5, ZC3H13, and TRDMT1 were predominantly expressed within epithelial clusters, consistent with a tumor-intrinsic regulatory role." (PMID 40565233, 2025).
tumor (continued). "HSPA4 overexpression upregulates ALKBH5 via increasing its protein stability, leading to decrease of CD58 of tumor cells and increase of PD1/PDL1 axis, finally to impair the toxicity of CD8+ T cells and immune evasion of GC cells." (PMID 38589927, 2024). "Its antisense RNA, LncRNA GAS5-AS1, enhances GAS5 stability by acting on the demethylase ALKBH5 and regulating GAS5 m6A modification, thereby inhibiting tumor cell proliferation, invasion, migration, and metastasis." (PMID 39473440, 2024). "The m6A demethylase, ALKBH5, decreases YTHDF-mediated YAP expression to suppress tumor growth and metastasis in NSCLC cells." (PMID 39691597, 2024). "In consistent, high expression of ALKBH5 can restrain HCC metastasis, thus suggesting a tumor-suppressive function of ALKBH5 in HCC progression." (PMID 38545555, 2024). "Inhibition of tumor cell proliferation can be achieved by blocking METTL3, TRMT6/TRMT61A, the IGF2BP family, YTHDF2, or ALKBH5." (PMID 39372415, 2024). "Thereafter, we established the xenograft mouse model and found that MIR205HG downregulation suppressed tumor growth and reduced the positive rate of Ki67, together with reductions in JMJD2C and ALKBH5 levels in tumors." (PMID 38252669, 2024). "As an ALKBH5 inhibitor, the mechanisms of IOX3, which is related to tumor angiogenesis, need further investigation to provide new drug directions for cancer treatment." (PMID 39295872, 2024). "Univariate regression analysis demonstrated that advanced tumor stages (III & IV) and high expression of ALKBH5 were both hazard factors of OS." (PMID 38481816, 2024). "Through a series of functional assays, we proved that ALKBH5 acted as an oncogene in SKCM via facilitating cell migration, invasion, proliferation, colony formation, and inhibiting autophagy, leading to tumor advancement and metastasis." (PMID 38481816, 2024). "Increasing evidence shows that ALKBH5 and IGF2BP2 are closely related to tumor growth, proliferation, and survival." (PMID 39281280, 2024). "Knockout of ALKBH5 leads to reduced TAMs, increased CD8+ T-cell infiltration, and increased tumor sensitivity to immunotherapy." (PMID 39726589, 2024). "Subsequently, direct interaction between ALKBH5 and CARMN was confirmed via RIP assay in both human tissue and mouse xenograft tumours." (PMID 39039912, 2024). "ALKBH5 demethylates lncRNA KCNK15-AS1, is decreased in pancreatic cancer, resulting in reduced tumor migration, invasion, and EMT." (PMID 39457524, 2024). "Mechanically speaking, ALKBH5 recognized the m6A motif on ABCA1 3'UTR, lowering its mRNA stability and protein expression to facilitate tumor advance." (PMID 38481816, 2024). "Mechanistically, ALKBH5 inhibits ACC1 deacetylation by promoting SIRT3 methylation, and the resulting downregulation of ACC1 expression ultimately inhibits tumor growth, lipid metabolism, and tumorigenesis." (PMID 39759516, 2024). "ALKBH5 is decreased in non-small cell lung cancer and reduces m6A levels on YAP pre-mRNA, leading to suppressed tumor proliferation, migration, invasion, and EMT." (PMID 39457524, 2024). "ALKBH5 is positively correlated with PD-L1 expression in human NSCLC tissues, while macrophages and tumor cells are the main sources of PD-L1 in the TME." (PMID 38872221, 2024). "A follow-up trial showed that knockdown of ALKBH5 in the human BC cell line MDA-MB-231 reduced BCSC numbers and consequently significantly reduced their capacity for tumour initiation." (PMID 38711100, 2024). "Knocking out ALKBH5 in glioma or targeting it with IOX1 reduces the expression of the PD-L1 protein, inhibits tumor growth, extends the survival of mice, and enhances these effects of PD-1 blockade therapy." (PMID 39372415, 2024).
tumor (continued). "For further investigation of the relationship between ALKBH5/LINC00659 and JAK1 in the GC, we validated the JAK1 expression in tumours harvested from nude mice with LINC00659/ALKBH5 abnormally expressed and the paired controlled ones." (PMID 36864711, 2023). "Except for ALKBH5, related studies have reported the role of some m6A regulators, such as METTL3 and FTO, in the induction of tumour radiation resistance." (PMID 36792369, 2023). "Functionally, ALKBH5 promoted the proliferative, migrative and invasive abilities of CRC cells in vitro and enhanced subcutaneous tumour growth in vivo." (PMID 37203239, 2023). "To explore the expression of ALKBH5 in CRC, we first detected the levels of mRNA and protein in fresh frozen tumours and matched adjacent normal tissues using qPCR, WB and IHC assays, respectively." (PMID 37203239, 2023). "For chemoresistance in ESCC, the highly overexpressed ALKBH5-induced lncRNA CASC8 activate the Bcl2/Caspase3 pathway to decrease the cisplatin sensitivity of ESCC and promote tumor development." (PMID 37063421, 2023). "Specific inhibitors of m6A regulators have demonstrated exciting anti-tumor effects, including inhibitors of METTL3, FTO, ALKBH5, IGF2BP1, while the therapeutic effects of METTL3 activators remain unverified." (PMID 36810281, 2023). "Dong and his colleagues found that ALKBH5 expression induced by hypoxia promoted the recruitment of TAMs in GBM and an immunosuppressive microenvironment in allograft tumours." (PMID 36859310, 2023). "The expression of HIF-1α, ALKBH5, and lymphatic density (LYVE-1 marker) was significantly elevated in tumor tissues." (PMID 36632222, 2023). "Firstly, it is worth noting that ALKBH5 and FTO act as oncogenes or tumor suppressors in some cancers." (PMID 37007161, 2023). "Integrative transcriptome and m6A-seq analyses showed that ALKBH5 can demethylate the mRNA of the transcription factor FOXM1, thus leading to enhanced expression levels of FOXM1 and the recovery of tumor growth." (PMID 37007137, 2023). "HCC patients with high ALKBH5 and TIRAP expression were prone to radiation‐induced liver injury and poor tumour response to radiotherapy." (PMID 36792369, 2023). "ALKBH5 suppresses casein kinase 2 (CK2) α-mediated glycolysis in bladder cancer (BCa), enhancing the sensitivity of tumour cells to cisplatin." (PMID 36859310, 2023). "Another study showed that ALKBH5 is up‐regulated in hepatitis B virus (HBV) HCC tissues and has a tumour‐promoting effect and predicts a poor prognosis." (PMID 36792369, 2023). "In mechanism, ALKBH5 deletion reduces MCT4 expression and lactate content in tumor interstitial fluids, which ultimately suppressed the Treg and polymorphonuclear myeloid derived cell." (PMID 36810281, 2023). "Thus, ALKBH5 could predict responses to anti-tumor immunotherapy." (PMID 36835633, 2023). "For instance, hypoxia stimulates HIF-1α- and HIF-2α-dependent expression of ALKBH5, which demethylates NANOG mRNA and increased the percentage of breast CSCs in the tumor microenvironment." (PMID 37015927, 2023). "ALKBH5 and FTO immunostaining in the OSCC group were observed in both the peripheral and central areas of the tumor islands." (PMID 36582218, 2023). "Studies have demonstrated that ALKBH5 demethylates KCNK15-AS1 and participates in KCNK15-AS1-mediated cell migration and invasion, hence regulating tumor growth." (PMID 36831377, 2023). "Heatmap analysis showed that 10 m6A regulators were significantly more highly expressed in tumour tissue than in normal tissue (p < 0.05), except for FTO and ALKBH5." (PMID 35189810, 2022). "Following the Venn diagram analysis of 601 genes related to ALKBH5 expression following WGCNA, 1027 tumor stem cell-related marker genes and 465 order genes with alteration in tumor following scRNA-seq data analysis, a total of 45 key genes were identified." (PMID 36551544, 2022).